MACC1 (MET transcriptional regulator MACC1)
Diseases named in the same sentence as MACC1 in open-access papers (continued):
Sharing a sentence is not in itself a finding about the gene and the disease.
pancreatic cancer (17 papers, 2014 to 2025). "The metastasis of pancreatic cancer is associated with colon cancer protein 1 (MACC1), which positively interacts with SNAI1; this interaction represses CDH1 (which encodes E-cadherin) and enhances fibronectin 1 (FN1) expression, which promotes cell migration." (PMID 39941895, 2025). "In the same year it was found that in pancreatic cancer cells IFN-γ inhibited MACC1 expression in a time and concentration dependent manner, leading to reduced cellular proliferation, migration, and downregulation of phosphorylated AKT and phosphorylated mTOR." (PMID 39580452, 2024). "Various research groups have elucidated the effects of MACC1 on mechanisms of resistance towards chemotherapeutic drugs across a wide range of tumor types, including glioblastoma, colorectal, gastric, and pancreatic cancers." (PMID 39580452, 2024). "MACC1-enhanced transcriptional events contribute to epithelial–mesenchymal transition (EMT) in pancreatic cancer cells." (PMID 38396744, 2024). "Overexpression or knockdown of MACC1 in PC cells correspondingly promoted or inhibited pancreatic cancer cell migration and invasion in a MET proto-oncogene receptor tyrosine kinase (MET)-independent manner." (PMID 36333284, 2022). "Correlations of circulating MACC1 transcripts and MACC1 protein expression with survival for lung and pancreatic cancer patients were also reported." (PMID 27439755, 2016). "Interestingly, in pancreatic cancer MACC1 can also convey chemoresistance towards gemcitabine by stabilizing the expression of Gab2, Ras and pERK1/2." (PMID 39580452, 2024). "In addition to Lovastatin, several other statins including Fulvastatin, Atorvastatin, Simvastatin and Pitavastatin have also been found to reduce Macc1 expression in multiple cancer cell lines including colorectal, gastric and pancreatic cancer." (PMID 37841442, 2023). "However, the prometastatic role of MACC1 in regulating the pancreatic cancer (PC) metastatic phenotype remains elusive." (PMID 36333284, 2022). "In addition, the role of exosomes circRNA circ‐PDE8A in regulating the invasion of pancreatic cancer through the miR‐338/MACC1/MET pathway has also been described." (PMID 35446993, 2022). "Collectively, our results unveil a new mechanism by which MACC1 drives pancreatic cancer cell metastasis and suggest that the MACC1-SNAI1 complex-mediated mesenchymal transition may be a therapeutic target in pancreatic cancer." (PMID 36333284, 2022). "Tumor-released exosomal circRNA PDE8A promotes invasive growth via the miR-338/MACC1/MET pathway in pancreatic cancer, which may be involved in the remodeling of the extracellular matrix." (PMID 35114891, 2022). "Exosomal circRNA PDE8A promotes pancreatic cancer invasion via the miR-338/MACC1/MET pathway." (PMID 33867829, 2021). "Exosomal-PDE8A induces cell development via the miR-338/MACC1/MET pathway in pancreatic cancer." (PMID 33109773, 2020). "CircRNA PDE8A in sEVs can promote the occurrence and development of pancreatic cancer through Mir-338 /MACC1/MET pathway, which has a significant role in the progression of pancreatic cancer and can be as a potential biomarker." (PMID 34980146, 2022). "Among them, BxPC-3 cells displayed the highest expression level of MACC1, which was derived from primary pancreatic cancer, while PANC-1 and SUIT-2 cells exhibited the lowest expression level of MACC1." (PMID 36333284, 2022). "The exact reason why MACC1 does not promote metastasis via MET in pancreatic cancer is likely complex and deserves further analysis." (PMID 36333284, 2022). "This was further corroborated in pancreatic cancer, where the c-MET inhibitor JNJ-38877605 did not prevent direct protein–protein interaction of MACC1 with the EMT-marker SNAI1, resulting in the upregulation of fibronectin 1 (FN1) and a repression of E-cadherin." (PMID 39580452, 2024).
pancreatic cancer (continued). "Third, MACC1 is not the only regulator of MET, and there are many proteins other than MACC1 that can directly regulate MET expression (e.g., HIF1, SP1, AP1, and Ets-1), suggesting that MACC1 may not be a predominant regulator of MET in pancreatic cancer." (PMID 36333284, 2022).
lung adenocarcinoma (16 papers, 2012 to 2025). A carcinoma that arises from the lung and is characterized by the presence of malignant glandular epithelial cells. "Our previous studies also have shown that MACC1 is highly expressed in lung adenocarcinoma, overexpression of MACC1 is an independent risk factor for poor prognosis in patients with lung adenocarcinoma." (PMID 39695175, 2024). "Many studies have suggested that MACC1 overexpression is associated with a range of malignant tumours in humans and with postoperative recurrence of lung adenocarcinoma." (PMID 39544485, 2024). "In lung adenocarcinoma, high levels of MACC1 expression have been shown to be associated with postoperative recurrence of tumors." (PMID 33712897, 2021). "Overexpression of MACC1 paracrine signaling in carcinoma-associated fibroblasts has been shown to contribute to invasion by lung adenocarcinoma cells." (PMID 33425885, 2020). "This suggests that MACC1 influences the splicing outcomes of specific genes by regulating hnRNPH1 activity, which was observed in a lung adenocarcinoma model." (PMID 40507967, 2025). "Intriguingly, depletion of YBX1 has been found to decrease metastasis associated in colon cancer-1 (MACC1) promoter activity, thus abolishing MACC1/c-Met signaling in lung adenocarcinoma cells." (PMID 37381723, 2023). "Shimokava and colleagues demonstrated this role of MACC1 in 146 consecutive patients who underwent a complete resection for stage I lung adenocarcinoma." (PMID 35406521, 2022). "Collectively, our data suggested that targeting YB-1 suppressed lung adenocarcinoma progression through the MACC1/c-Met pathway and that the high expression of YB-1/MACC1 is a potential prognostic marker in lung adenocarcinoma." (PMID 28624808, 2017). "In the present study, the 179 patients with lung adenocarcinoma that showed high expression of YB-1 and MACC1 had shorter 5-year overall survival than patients with low expression of YB-1 and MACC1." (PMID 28624808, 2017). "Depletion of YB-1 markedly decreased MACC1 promoter activity and suppressed the MACC1/c-Met signaling pathway in lung adenocarcinoma cells." (PMID 28624808, 2017). "Both YB-1 and MACC1 were elevated in human lung adenocarcinoma cell lines (A549 and H1299), compared to human bronchial epithelial cell (HBE cells), and were mainly detected in the cytoplasm in these cells." (PMID 28624808, 2017). "Collectively, we demonstrated that YB-1 promoted lung adenocarcinoma growth and progression in vitro and in vivo through directly binding to the MACC1 promoter and enhancing MACC1/c-Met pathway." (PMID 28624808, 2017). "Subsequently, we analyzed different lung cancer cell lines and 5 lung adenocarcinoma tissue specimens by Western blot assay to verify the correlation between YB-1 and MACC1." (PMID 28624808, 2017). "These new data reveal a valuable understanding regarding the regulation of MACC1 and provide a new therapeutic target in lung adenocarcinoma." (PMID 28624808, 2017). "MACC1 knockdown effectively inhibited proliferation and promoted apoptosis of lung adenocarcinoma cells by regulating the β-catenin pathway (including c-myc), and DBC1 (BMP/retinoic acid inducible neural specific, which play a key role in CRC progression through Wnt/β-catenin-MACC1 signaling axis." (PMID 35406521, 2022). "Moreover, YB-1 was positively correlated with MACC1, and both proteins were over-expressed in lung adenocarcinoma tissues." (PMID 28624808, 2017). "Our study provides compelling evidence to suggest that targeting the YB-1/MACC1/c-Met axis could be a potential therapeutic strategy for lung adenocarcinoma patients." (PMID 28624808, 2017). "Our founding also indicated that YB-1 is an independent prognostic indicator for lung adenocarcinoma patients, and targeting YB-1/MACC1/c-Met axis could be a promising strategy for tumor intervention and therapy." (PMID 28624808, 2017).
lung adenocarcinoma (continued). "We previously reported that MACC1 was a useful marker for predicting postoperative recurrence in patients with lung adenocarcinoma following surgery, and MACC1 promoted lung adenocarcinoma progression, the mechanisms underlying its function are poorly understood." (PMID 28624808, 2017). "The multivariate analysis of risk factors showed that high TNM stage and high YB-1 expression, but not MACC1 or the combination of YB-1 and MACC1, were independent prognostic risk factors in lung adenocarcinoma." (PMID 28624808, 2017). "Thus, we proceeded to evaluate the correlation between YB-1 and MACC1 mRNA and protein expression in lung adenocarcinoma A549 cells." (PMID 28624808, 2017). "Furthermore, YB-1 expression was positively correlated with MACC1 expression in the 179 lung adenocarcinoma tissue specimens." (PMID 28624808, 2017). "Furthermore, we previously found that both YB-1 and MACC1 were over-expressed in lung adenocarcinoma tissue, and their expression correlated with tumor metastasis in lung adenocarcinoma." (PMID 28624808, 2017). "Similarly, the 5-year OS rate of lung adenocarcinoma patients with high MACC1 was 61.9%, which was lower than those of patients with low MACC1 (74.3%; p=0.028)." (PMID 28624808, 2017). "MACC1 expression may be a useful marker for predicting postoperative recurrence in patients with lung adenocarcinoma after surgery." (PMID 23573286, 2013). "In the research of lung adenocarcinoma, YB1 is positively associated with TNM stages and cancer differentiation and patients with high expression of YB1 had poorer survival outcomes, and deeper study revealed that metastasis associated in colon cancer-1 (MACC1) was the target of YB16." (PMID 35260638, 2022). "Moreover, MACC1 has also been reported to increase the proliferative and apoptotic capacity of lung adenocarcinoma cells by acting on the β-catenin pathway, suggesting that MACC1 might regulate tumor progression through various signaling pathways." (PMID 33425885, 2020). "Likewise, in the lung adenocarcinoma tissue specimens, the expression level of YB-1 and MACC1 were also much higher than in the normal lung tissues adjacent to tumor lesions, and YB-1 expression was positively correlated with MACC1 expression (R2=0.8136, p<0.0004)." (PMID 28624808, 2017). "In lung adenocarcinoma, hnRNPH1 interacts with the MACC1 protein (via its GYR domain binding to the MACC1 SH3 domain) to prevent the skipping of exon 11 in the IRAK1 gene’s pre-mRNA, thereby promoting the production of the oncogenic IRAK1-L isoform, driving tumorigenesis." (PMID 40507967, 2025). "In addition, our data revealed that the expression of YB-1 is positively correlated with MACC1 and that both proteins are over-expressed in lung adenocarcinoma tissues, compared to adjacent non-tumor tissues." (PMID 28624808, 2017).
lung cancer (16 papers, 2011 to 2025). A malignant neoplasm involving the lung. "While MACC1 has been well studied in several cancers, including colon, gastric, and lung cancers, its role in EC remains less explored." (PMID 40354443, 2025). "Nowadays, MACC1 has been confirmed to be a key regulator of malignant proliferation and metastasis in various solid tumor, including lung cancer." (PMID 39695175, 2024). "We stably knocked down MACC1 in two lung cancer cell lines of lung cancer cells (H1299, H2170), and set up two short hairpin RNA knockdown sequences to prevent the off-target effect of si-RNA." (PMID 39695175, 2024). "MACC1 was also upregulated in the stemness-enriched cell subsets of lung cancer according to the GEO database." (PMID 39695175, 2024). "To further explore the connection between MACC1 and lung cancer stem cells, we firstly analyzed the gene expression profiles of lung cancer cells TUM622 under 3D and 2D culture conditions." (PMID 39695175, 2024). "Surprisingly, we found that the expression level of mature miR-25, miR-25-3p was also down-regulated after MACC1 knockdown by RT-qPCR in lung cancer cell line, consistent with previous reports." (PMID 39695175, 2024). "Taken together, these results indicated that KLF4 is a key effector for the MACC1 silence suppress stem-like properties in lung cancer." (PMID 39695175, 2024). "KLF4 protein levels were significantly upregulated when MACC1 was knocked down in lung cancer cell lines H1299 and H2170." (PMID 39695175, 2024). "Metastasis-associated in colon cancer-1 (MACC1) was identified as a new player in lung cancer development, and some stemness-related genes can be novel transcriptional targets of MACC1." (PMID 39695175, 2024). "The results showed that YB-1 and MACC1 were over-expressed in these different lung cancer cell lines, compared to human fetal lung fibroblasts (HFL-1)." (PMID 28624808, 2017). "MACC1 and c-met expressions were significantly higher in lung cancer tissues than that in neighboring normal tissue (P < 0.001)." (PMID 22814258, 2012). "Consistently, growing evidence indicates that YB-1 and MACC1 could be prognostic predictors for various tumors, including lung cancer." (PMID 28624808, 2017). "Several studies have investigated the influence of MACC1 mRNA levels on the clinical outcome in patients with colorectal, gastric and lung cancer, respectively, providing evidence that MACC1 overexpression is a crucial prognostic factor for tumor recurrence, metastasis, and survival." (PMID 22251819, 2012). "MACC1 and c-met expressions were detected in 103 cases of NSCLC and 40 cases of neighboring normal lung cancer tissue using immunohistochemistry." (PMID 22814258, 2012). "To further inspect the role of MACC1 in non-CSCs dedifferentiation of lung cancer in vivo, we conducted tumor formation experiments in nude mice (BALB/c)." (PMID 39695175, 2024). "We provide evidence in this study showing that non-CSCs dedifferentiation process also exists in lung cancer cells, and uncovered here for the first time that MACC1 was enriched in the lung CSCs subpopulations." (PMID 39695175, 2024). "To better explore the potential mechanism of MACC1 mediated non-CSCs dedifferentiation, we performed RNA-seq of lung cancer cells (NCI-H1299) stably knocked down MACC1 and control." (PMID 39695175, 2024). "Here, we showed that MACC1 promoted the transition from non-CSC to CSC in lung cancer." (PMID 39695175, 2024). "Therefore, KLF4 can be used as a negative regulator of cancer stem cells in lung cancer, and it is also consistent with the result of knocking down MACC1 to inhibit the dedifferentiation of non-CSCs in lung cancer by up-regulating the expression of KLF4." (PMID 39695175, 2024).
lung cancer (continued). "To test whether MACC1 regulate KLF4 via miR-25 and to determine whether the reduced expression of miR-25 was responsible for MACC1 silence mediated stabilization of KLF4 mRNA, we performed rescue experiments by transfecting miR-25 mimics in MACC1 stably knockdown in lung cancer cells." (PMID 39695175, 2024). "Given that the CSC subpopulation in cancer can be maintained by non-CSC dedifferentiation, we sought to evaluate whether non-CSC dedifferentiation exists in lung cancer cells, and determine the role of MACC1 in non-CSCs dedifferentiation." (PMID 39695175, 2024). "However, the potential mechanism for MACC1-mediated lung cancer malignant proliferation remains uncertain, particularly the role of MACC1 participating in the process of non-CSCs dedifferentiation is still poorly characterized." (PMID 39695175, 2024). "To further verify the correlation between MACC1 and lung cancer CSCs, we used ALDH flow cytometry sorting technology and sphere formation assay to isolate lung cancer cells with stem-like properties, and identify MACC1 expression levels with rest non-stem cell subsets." (PMID 39695175, 2024). "Hence, we speculate that KLF4 may serve as a downstream regulatory target of MACC1 mediated non-CSCs dedifferentiation in lung cancer." (PMID 39695175, 2024). "High-throughput sequencing and tumor specimen analysis revealed that MACC1 was negative correlated with Krüppel-like factor 4 (KLF4) expression level, which acts as a negative stemness regulator in lung cancer." (PMID 39695175, 2024). "While MACC1 exerts its prometastatic effects by activating MET in various human cancers, including colon, gastric, liver and lung cancer, its prometastatic effects in PC are independent of MET activation according to our study." (PMID 36333284, 2022). "In addition, the opposite result was confirmed by Dox-induced MACC1 overexpressing of A549 ALDH- subpopulation after 7 days culture, supporting the role of MACC1 in modulating non-CSC-to-CSC conversions in lung cancer cell line." (PMID 39695175, 2024).